ITGA2B (integrin subunit alpha 2b)
Diseases named in the same sentence as ITGA2B in open-access papers (continued):
Sharing a sentence is not in itself a finding about the gene and the disease.
breast carcinoma (17 papers, 2013 to 2025). "Expression of ITGA2B was reported to be debilitating to some tumor cells such as breast cancer cells, which resulted in changing of the malignant phenotype to normal." (PMID 27806706, 2016). "Integrin alpha 2b (ITGA2B) is a member of the integrin family that regulates a diverse set of cellular processes and is crucial to the initiation, progression and metastasis of solid tumors, including breast cancer." (PMID 33573289, 2021). "The over-expression of ITGA2B promotes proliferation and invasion in breast cancer." (PMID 33573289, 2021). "Our data suggest that the results are robust in different NSCLC datasets and the key target genes identified (ITGA2B, FLNA, GRB2, FCGR2A, and APP, etc.)seem to also be strongly expressed in the breast cancer and pancreatic cancer datasets we analyzed." (PMID 41226816, 2025). "Model 2 included four candidate predictors specific for breast cancer in this study: Ras-related protein Rap-1A (RAP1A, LVVLGSGGVGK), Integrin alpha-IIb (ITGA2B, VYLFLQPR), FLNA (ANLPQSFQVDTSK), and Talin-1 (TLN1, LAQAAQSSVATITR)." (PMID 33267867, 2020).
leukemia (14 papers, 2010 to 2023). A malignant (clonal) hematologic disorder, involving hematopoietic stem cells and characterized by the presence of primitive or atypical myeloid or lymphoid cells in the bone marrow and the blood. "Herein we show that in leukemia cells ERG overexpression promotes a mesenchymal-like gene expression signature that includes: CD24, CD44, ITGA10, ITGB5, ITGB3, ITGA2B and the morphogenic-associated genes, such as SHANK3, TYROBP." (PMID 24504051, 2014).
acute coronary syndrome (13 papers, 2010 to 2026). Signs and symptoms related to acute ischemia of the myocardium secondary to coronary artery disease. "ITGB3 and ITGA2B as platelet glycoprotein IIb of IIb/IIIa which has already been used as therapeutic target to block platelet aggregation in acute coronary syndrome." (PMID 31534454, 2019).
bleeding disorder (11 papers, 2013 to 2025). "GT is caused by mutations in the genes encoding ITGA2B or ITGB3 that result in qualitative or quantitative abnormalities in the platelet membrane proteins leading to bleeding disorders." (PMID 26096001, 2016). "Additionally, SP1NK5, ITGA2B, and CR2 exhibit diverse implications, linking to Netherton syndrome, bleeding disorders, and common variable immunodeficiency, respectively." (PMID 38890201, 2024).
Hypertension (9 papers, 2014 to 2026). The presence of chronic increased pressure in the systemic arterial system. "Among those, CMTM5, ITGA2B, and SLC24A3 are implicated in platelet function and cardiovascular complications, whereas ENOSF1 has been previously linked to hypertension." (PMID 41500120, 2026).
Macrothrombocytopenia (9 papers, 2013 to 2026). "Current research suggests that gain‐of‐function mutations in ITGA2B or ITGB3 underlie the pathogenesis of most ITGA2B/ITGB3‐related macrothrombocytopenia and mechanistically distinguish it from classical GT." (PMID 41503871, 2026). "The αIIbArg995‐to‐Trp mutation is the most common mutation type of ITGA2B/ITGB3‐related macrothrombocytopenia in Japan." (PMID 41503871, 2026). "Complete loss of ITGA2B transcript and protein expression was verified by RT‐PCR and flow cytometry, explaining the underlying etiology of GT, and likely macrothrombocytopenia, in this cat." (PMID 38426552, 2024). "We also demonstrate one patient who showed compound heterozygote with ITGA2B p.Gly991Cys and a novel nonsense mutation in ITGA2B p.Arg422*, leading to GT-like marked reduction in surface αIIbβ3 expression levels associated with macrothrombocytopenia." (PMID 24498605, 2013). "However, recent reports have documented non‐activating ITGB3 mutations that also cause macrothrombocytopenia, presenting a profound challenge to the mechanistic understanding of ITGA2B/ITGB3‐related macrothrombocytopenia." (PMID 41503871, 2026). "The first case was a compound heterozygous mutation Gly991‐to‐Cys and Arg422* (Arg422 mutated to stop codon) of ITGA2B, resulting in only 3% to 11% of αIIbβ3 surface expression and 60% retention within the cell, and a severe GT‐like phenotype with macrothrombocytopenia." (PMID 41503871, 2026). "Furthermore, we found case 1 was a compound heterozygote of ITGA2B p.Gly991Cys and a novel nonsense mutation, ITGA2B p.Arg422*, and her platelets showed GT-like phenotype with macrothrombocytopenia." (PMID 24498605, 2013). "Ultimately, these efforts will enable precision therapeutic targeting based on mutational profiles, thereby improving clinical management of ITGA2B/ITGB3‐related macrothrombocytopenia." (PMID 41503871, 2026). "Although functional assays to evaluate spontaneous activation of integrin αIIbβ3 were not conducted, the current evidence supports the diagnosis of ITGA2B/ITGB3‐related macrothrombocytopenia." (PMID 41503871, 2026). "While classical GT typically exhibits normal platelet counts and morphology, very rare mutations in ITGA2B (encoding αIIb) and/or ITGB3 (encoding β3) cause macrothrombocytopenia or increased platelet anisotropy (heterogeneity of platelet size and morphology)." (PMID 41503871, 2026). "For over two decades, cases of mutations in ITGA2B or ITGB3 accompanied by spontaneous activation of αIIbβ3 and macrothrombocytopenia have been reported in clinical practice." (PMID 41503871, 2026). "Although the two types of αIIbβ3 mutations downregulate RhoA through different molecular mechanisms, targeted modulation of the RhoA/ROCK pathway may represent a therapeutic strategy for ITGA2B/ITGB3‐related macrothrombocytopenia." (PMID 41503871, 2026). "This review summarises the reported cases of gain‐of‐function mutations in ITGA2B and ITGB3 associated with ITGA2B/ITGB3‐related macrothrombocytopenia hitherto and discusses the potential molecular pathways contributing to the unique phenotypes in ITGA2B/ITGB3‐related macrothrombocytopenia." (PMID 41503871, 2026). "This particular type of disorder is called ITGA2B/ITGB3‐related macrothrombocytopenia and has been considered a subset of congenital macrothrombocytopenia." (PMID 41503871, 2026). "Examples include: BSS (GP1BA, GP1BB, GP9 genes); platelet-type von Willebrand disease (GP1B1); GT (ITGA2B and ITGB3); MYH9-RD if there is macrothrombocytopenia, Döhle bodies, and/or typical extra hematologic manifestations (MYH9)." (PMID 40563486, 2025). "MYH9-RD, mono and biallelic BSS and ITGA2B/ITGB3-RT are currently classified as inherited macrothrombocytopenias, while ANKRD26-RT has been reported to have platelets of normal size." (PMID 23617394, 2013).
Macrothrombocytopenia (continued). "Consequences of variants in ITGA2B and ITGB3 in GT patients were reported to cause lack of function, prevention of αIIbβ3 expression, and are associated with activated integrin defects and macrothrombocytopenia." (PMID 30792900, 2019).
lung carcinoma (8 papers, 2016 to 2025). "Quite similar patterns in the follow up tracing were observed for the lung cancer-related proteins ITGA2B, PH4B and 55 kDa F13A1." (PMID 34066760, 2021). "The abundance of both integrins of the fibrinogen receptor integrin αIIbβ3, ITGA2B and ITGB3, were significantly reduced in platelets of patients with lung cancer." (PMID 34066760, 2021). "Accordingly, lower levels of ITGA2B and increased levels of the ER proteins P4HB, CALR and HSPA5 in patients with lung cancer and LA suggest some common affected pathways in their prothrombotic pathology." (PMID 34066760, 2021). "In the test cohort, 56 (36.8%) of 152 patients with NSCLC were stage I. The relative expression levels of ITGA2B and SELP mRNA remained improved when only stage I lung cancer detection was involved (p < 0.001)." (PMID 31523198, 2019). "The ROC curves for platelet ITGA2B indicated a diagnosis of stage I lung cancer irrespective of CEA status." (PMID 31523198, 2019). "In conclusion, the current study clearly reveals that the platelet derived mRNA, ITGA2B and SELP are significantly increased in primary lung cancer patients thus could discriminating NSCLC and controls, and the combination of ITGA2B and CEA even performs better." (PMID 31523198, 2019).
systemic lupus erythematosus (6 papers, 2014 to 2025). An autoimmune multi-organ disease typically associated with vasculopathy and autoantibody production. "In fact, Zhai and colleagues have documented the presence of carboxyethylated ITGA2B also in PBMCs from patients with RA and systemic lupus erythematosus (SLE)." (PMID 37463891, 2023).
Arterial thrombosis (4 papers, 2012 to 2026). The formation of a blood clot inside an artery. "ITGA2B (Integrin alpha-IIb) was reported to aggravate the arterial thrombosis in anti-phospholipid syndrome patients." (PMID 26813334, 2016).
coronary heart disease (4 papers, 2019 to 2024). "Lastly, coexpression network analysis was undertaken on smoking-related hub genes of coronary heart disease in GeneMANIA, and then, ITGA2B, ALOX12, ESLP, and CLU were acquired." (PMID 35096131, 2022).
non-small cell lung carcinoma (4 papers, 2019 to 2025). A group of at least three distinct histological types of lung cancer, including non-small cell squamous cell carcinoma, adenocarcinoma, and large cell carcinoma. "However, ITGA2B shows to be particularly enriched in platelet, non-small cell lung cancer cells (ProteomicsDB), and basophils (Human Protein Atlas)." (PMID 33267867, 2020).
Obesity (4 papers, 2014 to 2024). Accumulation of substantial excess body fat. "Two studies of the present systematic review found contradictory ITGA2B protein abundance results in obesity." (PMID 38703299, 2024). "ITGA2B levels were reported to be reduced in platelet particles from subjects with obesity using flow cytometry." (PMID 38703299, 2024).
platelet disorder (4 papers, 2015 to 2025). "Platelet disorders displayed a different pattern, with ITGA2B mutations accounting for 17% of cases, and no other gene exceeding the 3% frequency threshold." (PMID 40488813, 2025).
autosomal dominant macrothrombocytopenia (2 papers, 2020 to 2025). This syndrome is characterized by congenital thrombocytopenia associated with the presence of large platelets. "Finally, it is worth mentioning that a pathology related to GT is autosomal dominant macrothrombocytopenia caused by heterozygous variants in the ITGA2B and ITGB3 genes." (PMID 41301446, 2025). "Finally, it should be mentioned that a pathology related to GT is autosomal dominant macrothrombocytopenia, caused by heterozygous variants in the ITGA2B and ITGB3 genes." (PMID 41301446, 2025).
cognitive decline (2 papers, 2023 to 2025). "The biomarkers of platelet activation such as SELP and ITGA2B/glycoprotein IIb‐ITGB3/glycoprotein IIIa are increased in AD patients with faster cognitive decline compared with those with slow cognitive decline." (PMID 39757022, 2025).
endometriosis (2 papers, 2022). The growth of functional endometrial tissue in anatomic sites outside the uterine body. "Although the dysregulation of several Integrin subunits has been observed in endometriosis, our results show, in a complementary way, that the integrin beta-4 (ITGB4) receptor for laminin and integrin alpha-IIb (ITGA2B) were upregulated in the eutopic endometrium of women with endometriosis." (PMID 35204508, 2022).
hypertrophic cardiomyopathy (2 papers, 2025). A condition in which the myocardium is hypertrophied without an obvious cause. "ITGA2B is involved in a variety of pathophysiological processes, including platelet activation, blood pressure, and hypertrophic cardiomyopathy." (PMID 40198259, 2025). "We also observed enrichment in pathways associated with circadian entrainment (e.g., GNG11, GUCY1B1) and hypertrophic cardiomyopathy (e.g., ITGB3, ITGA2B, IL6), suggesting systemic disruptions in PitNET PBMCs." (PMID 41253784, 2025).
Insulin resistance (2 papers, 2019 to 2022). Increased resistance towards insulin, that is, diminished effectiveness of insulin in reducing blood glucose levels. "On the other hand, the negative correlations between downregulated integrins ITGB1 and ITGA2B and the same glycemic control variables and others related to body composition and insulin resistance suggest a similar role in the inhibition of phosphorylation in these kinases." (PMID 35628588, 2022).
Von Willebrand disease (2 papers, 2014 to 2022). von Willebrand disease (VWD) is a hereditary bleeding disorder caused by a genetic anomaly leading to quantitative, structural or functional abnormalities of the Willebrand factor (von Willebrand factor; VWF). "The study was conducted to determine Mutations/genetic alterations in type III von Willebrand disease and also to determine the association of different mutations, methylation status, ITGA2B/B3 mutations and alloimmunization with the severity of type III vWD." (PMID 35741733, 2022).
allergic dermatitis (1 paper, 2022). "A significant increase in platelet-leukocyte aggregates expressing ITGA2B was found in the blood of mice with chronic hapten-induced allergic dermatitis." (PMID 36699197, 2022).
fibrosis (1 paper, 2023). the formation of excess fibrous connective tissue in an organ or tissue in a reparative or reactive process. "By retracing the interaction between macrophages and HSC, we found that Thbs1 was derived from macrophages in the fibrosis model, and communicated with HSCs by interacting with the aVb3 (Itgb3) and a2Bb3 (Itga2b&Itgb3) complex receptors." (PMID 37724132, 2023).
inflammatory bowel disease (1 paper, 2025). A spectrum of small and large bowel inflammatory diseases of unknown etiology. "ITGA2B, F2RL3, PTGS1, and ADCY5 were associated with the platelet activation pathway, while IL18 was linked to inflammatory bowel disease (IBD) and the cytokine–cytokine receptor interaction pathways." (PMID 41157169, 2025).
meningioma (1 paper, 2020). A generally slow growing tumor attached to the dura mater. "The global proteomic analysis of meningioma patients in the current study revealed perturbations in several components of Integrin including ITGAV, ITGB2, ITGA2B, and ILKAP." (PMID 32974197, 2020).
Myocardial fibrosis (1 paper, 2026). "Cellular sequencing analysis of the two groups of mice reported that platelet‐associated Itga2b is a key mediator through which PCSK9 affects post‐AMI myocardial fibrosis." (PMID 41573336, 2026).
Parkinson disease (1 paper, 2020). A progressive degenerative disorder of the central nervous system characterized by loss of dopamine producing neurons in the substantia nigra and the presence of Lewy bodies in the substantia nigra and locus coeruleus. "An ITGA2B variant (rs5910), previously associated with Parkinson’s disease, was replicated in the TCX and PHG regions." (PMID 32492070, 2020).
pneumonia (1 paper, 2022). An acute, acute and chronic, or chronic inflammation focally or diffusely affecting the lung parenchyma, caused by an infection in one or both of the lungs (by bacteria, viruses, fungi, or mycoplasma.). "We measured the levels of four DEmRNAs (F13A1, ITGB3, ITGA2B and VWF) involved in platelet aggregation during SARS-CoV-2 infection in 5 patients with pneumonia and 6 normal donors by RT-qPCR." (PMID 35139909, 2022). "We found that the ITGA2B and VWF were significantly decreased in patients with pneumonia compared with control donors." (PMID 35139909, 2022).
pulmonary hypertension (1 paper, 2025). Increased pressure within the pulmonary circulation due to lung or heart disorder. "ITGA2B was highly expressed in the peripheral blood of patients suffering from pulmonary hypertension, proposing that ITGA2B is the hub protein of pulmonary hypertension." (PMID 40198259, 2025).
thyroid tumor (1 paper, 2023). A benign or malignant neoplasm affecting the thyroid gland. "Among the identified hub genes, AEBP1, CD34, COL12A1, ITGA2B, THBS2, and TPO exhibit lower expression levels in thyroid tumors." (PMID 37795451, 2023).
tumor (91 papers, 2009 to 2025). "Platelet ITGA2B had pinpoint diagnostic accuracy for all NSCLC, stage I NSCLC, and NSCLC with only one tumour of 2 cm or less." (PMID 31523198, 2019). "Remarkably, RNA sequencing revealed high baseline expression of Itga2b in LN LECs, with a 2-fold increase in LECs of 4T1 tumor-draining LNs and an almost 3-fold increase in the B16F10 model." (PMID 30590031, 2018). "The presence of circulating ITGA2B may indicate an ongoing process of tumor cell-induced platelet aggregation." (PMID 33267867, 2020). "Molecular markers: Alongside established TEP biomarkers (ITGA2B, IGFBP2), PSG2 indicates tumor-derived RNA uptake." (PMID 41226816, 2025). "A particularly interesting potential interaction with high relevance for tumor biology includes JAG2 (cancer) with NOTCH3 (mouse stroma), and interactions of integrins (ITGA2, ITGA2B) with ECM proteins (COL2A1, LAMA1)." (PMID 35053442, 2022). "ITGA2B (integrin alpha-IIb;CD41) and ITGB3 (integrin alpha-V beta 3;CD61) can be expressed by CTCs and are critical for the platelet-cancer cell interaction, as inhibition of ITGB3 prevents the platelet-tumour cell interactions." (PMID 33789677, 2021). "We further explored whether ITGA2B can supplement CEA, the most common clinical used tumor marker in NSCLC and routine physical." (PMID 31523198, 2019). "The tumor platelets could perhaps behave in a 'semi-activational state'23 but absence of activation, and overexpressed the ITGA2B and SELP mRNA but not protein in the initial of tumorgenesis." (PMID 31523198, 2019). "Co-expression analysis indicated that ITGA5 mRNA expression had a significantly positive correlation with ITGB5 (r=0.32, P<0.001) in tumor tissue, whereas ITGA2B had a significantly negative correlation with ITGA5 (r=-0.142, P =0.035) and ITGB5 (r=-0.34, P <0.001), respectively." (PMID 29100351, 2017). "In contrast, the expression of ITGA2B was the opposite, and significantly negative correlation with ITGA5 and ITGB5 in tumor tissue." (PMID 29100351, 2017).
cancer (40 papers, 2015 to 2026). A tumor composed of atypical neoplastic, often pleomorphic cells that invade other tissues. "These analyses identified ITGA2B and FLNA consistently upregulated and functionally relevant in platelet signaling and cancer-associated thrombosis." (PMID 41226816, 2025). "Taken together, our integrative strategy revealed ITGA2B, FLNA, GRB2, FCGR2A, and APP as high-confidence, FDA-targetable candidates that intersect cancer-associated platelet education with pro-metastatic platelet signaling." (PMID 41226816, 2025). "When we made classification models with ITGA2B alone, the highest AUC obtained was 0.78 on the pan-cancer dataset." (PMID 33287695, 2020). "The log fold changes and, thus, the rankings among all the DEGs are almost the same for each of the found key genes ITGA2B, FLNA, GRB2, FCGR2A, and APP across all three datasets, confirming that these are consistently differentially expressed in NSCLC vs. healthy/non-cancer." (PMID 41226816, 2025). "The truncated isoform of integrin ITGA2B lacking the transmembrane domain is another example, which was previously reported to be secreted into the ECM in various cancers, breaking adhesion and facilitating cell migration." (PMID 36509773, 2022).